HIF1A (hypoxia inducible factor 1 subunit alpha)
Diseases named in the same sentence as HIF1A in open-access papers (continued):
Sharing a sentence is not in itself a finding about the gene and the disease.
visceral leishmaniasis (9 papers, 2017 to 2025). A severe form of leishmaniasis characterized by irregular bouts of fever, substantial weight loss, swelling of the spleen and liver, and anemia (which may be serious). "Correspondingly, HIF-1α expression has been detected in both cutaneous lesions (37, –, 39) and in the spleens of mice infected with parasites causing visceral leishmaniasis." (PMID 40512023, 2025). "Taken together, these findings suggest that low oxygen levels and HIF-1α play a detrimental role in innate immunity during visceral leishmaniasis by impairing the functionality of dendritic cells and promoting immunosuppressive pathways in T cells." (PMID 40512023, 2025). "HIF-1α expression in mononuclear phagocytes favors the development of visceral leishmaniasis in the spleen and bone marrow, while HIF-1α in myeloid cells decreases L. major and cutaneous." (PMID 36015018, 2022). "In previous studies on visceral leishmaniasis models, HIF1α was essential for a host-protective response during L. donovani infection in vitro and in vivo." (PMID 36685903, 2022). "In a visceral leishmaniasis infection model, excess secretion of HIF-1α from DCs inhibited the production of IL-12, decreasing the number of Th1 subtypes." (PMID 35155430, 2022). "In the experimental model of chronic visceral leishmaniasis, it has been shown that HIF-1a contributes to L. donovani infection establishment, through abrogation of IL-12 production by splenic DCs leading to limited expansion of the Th1 cell." (PMID 35888991, 2022). "During visceral leishmaniasis, HIF-1α stabilization is also induced in uninfected cells by the inflammatory environment and appears to hamper DC functions." (PMID 28892492, 2017). "Taken together, these findings demonstrate that HIF-1α expression in CD11c+ mononuclear phagocytes favors development of visceral leishmaniasis in spleen and bone marrow, while HIF-1α in LysM+ myeloid cells supports defense against cutaneous L. major infection." (PMID 29520262, 2018). "While HIF-1α in mononuclear phagocytes is protective in L. major-induced cutaneous leishmaniasis, HIF-1α expression in these cells emerged as detrimental factor in visceral leishmaniasis." (PMID 29520262, 2018). "Moreover, we have reported that HIF-1α stabilization in dendritic cells inhibited their function and consequently limited the expansion of protective CD8 T cell responses during experimental visceral leishmaniasis (VL)." (PMID 28892492, 2017).
acute respiratory distress syndrome (8 papers, 2021 to 2025). Progressive and life-threatening pulmonary distress in the absence of an underlying pulmonary condition, usually following major trauma or surgery. "HIF-1α has recently been shown to play a critical role in the acute inflammatory response associated with acute respiratory distress syndrome (ARDS) associated with trauma and hemorrhagic shock." (PMID 33378321, 2021). "In this regard, a recent study reported that PSGL-1 expression increased susceptibility in patients with acute respiratory distress syndrome, demonstrating the PSGL-1 promoter activity was strongly regulated by HIF-1α and HIF-2α." (PMID 37854605, 2023). "Studies have demonstrated that HIF-1α loss in the alveolar epithelium exacerbates lung injury during acute respiratory distress syndrome (ARDS), indicating that HIF-1α and the glycolytic pathway play pivotal roles in ALI." (PMID 41562069, 2025). "This study demonstrates that Xanthoxylin exerts protective and anti-inflammatory effects by down-regulating and inhibiting the Akt/HIF-1α/NF-κB pathways, suggesting its potential as a therapeutic target for the prevention and treatment of ALI or acute respiratory distress syndrome (ARDS)." (PMID 39201430, 2024).
Anxiety (8 papers, 2023 to 2025). Intense feelings of nervousness, tension, or panic often arise in response to interpersonal stresses. "The expressions of angiogenic protein genes (NOS3, VEGF) and HIF-1a were decreased significantly in the current study in ewes showed anxiety temperament than the calm ones (P < 0.05)." (PMID 40625796, 2025). "Studies have found that abnormal activation of microglia (e.g., via the Warburg effect or Pyruvate Kinase M2/Hypoxia-Inducible Factor-1 alpha (PKM2/HIF-1α) pathway) can lead to synaptic dysfunction and anxiety-like behaviors." (PMID 41234418, 2025).
cervical tumor (8 papers, 2006 to 2024). "CAIX appears to be strictly regulated by hypoxia via HIF-1α and shows strong up-regulation in hypoxic regions of tumors of the cervix." (PMID 26502718, 2015). "An earlier report showed that thymosin beta-4-induced HIF-1α stabilization in human cervical tumor cells is ROS-dependent." (PMID 21980400, 2011). "We also detected the protein level of HIF-1α in cervical tumors of mice." (PMID 30355300, 2018). "Radiation suppressed the protein level of HIF-1α in cervical tumors (p = 3.64 × 10− 4)." (PMID 30355300, 2018). "Moreover, common signatures of both hypoxia and aerobic glucose metabolism, such as GLUT1, HK2, and HIF1A expression, are often found to be elevated in cervix tumors." (PMID 28804704, 2017). "In turn, it was demonstrated, that metformin inhibited HIF1A and suppressed the expression of glucose transporters (GLUT1, GLUT3) and regulatory enzymes of the glycolytic pathway in cervical tumor cells." (PMID 30217067, 2018). "Glut1, on the other hand, is also a HIF-1α target gene induced under hypoxia and its expression has been shown to correlate significantly with CA9 in cervix tumors from patients." (PMID 27901496, 2017). "High expression of HIF1A and its target proteins glucose transporter SLC2A1 (GLUT1) and pH regulator CA9 has been found in cervix tumors that were identified as hypoxic by pimonidazole staining or electrode measurements." (PMID 28804704, 2017).
cutaneous melanoma (8 papers, 2014 to 2025). A primary melanoma arising from atypical melanocytes in the skin. "Hypoxia and HIF-1α have also been linked to the tumorgenicity of cutaneous melanoma." (PMID 25166211, 2014). "Immunohistochemical analysis with antibodies adipophilin, FASN, GLUT‐1, HIF‐1α, and Ki‐67 was performed in a series of 28 sinonasal melanomas (SM), 16 oral melanomas (OM), and 39 cutaneous melanomas (CM)." (PMID 40867038, 2025). "Our analysis of two RNAseq datasets of human cutaneous melanoma revealed a positive correlation between HIF1α (or a geneset signature of the HIF1 signaling pathway) and PD-L1 expression." (PMID 34268602, 2022). "Cutaneous melanoma cells exposed to hypoxia have a higher HIF1α expression and lower MITF expression and give rise to larger tumours and more frequent metastases." (PMID 35682684, 2022). "Aligned with this, enhanced HIF1α expression impaired staurosporin-induced cell death in cutaneous melanoma cells." (PMID 35682684, 2022). "Previous studies have shown that NF-kB activity contributes to HIF-1α accumulation in cutaneous melanoma." (PMID 25166211, 2014). "Here, we examined relationships between HIF-1α and VEGF expression and nocturnal IH in cutaneous melanoma (CM) tumor samples." (PMID 29755400, 2018). "Moreover, HIF-1a and HIF-2a proteins are involved in melanogenesis and could be involved in cutaneous melanoma evolution." (PMID 36294785, 2022).
diffuse large B-cell lymphoma (8 papers, 2013 to 2025). "Several research groups have reported that elevated HIF-1α levels have been linked to poor prognoses in human diffuse large-B-cell lymphoma." (PMID 28489881, 2017). "Similarly, HIF-1α overexpression associated with increased survival in patients with diffuse large B-cell lymphoma." (PMID 28415662, 2017). "Studies have demonstrated that HIF-1α is activated in diffuse large B-cell lymphoma (DLBCL) cells under hypoxia conditions, thereby inducing the expression of HKII." (PMID 34220956, 2021). "Gene expression profiling studies have shown that increased expression of transcription factor Hypoxia Inducible Factor-1 alpha (HIF-1α) plays an important role in the pathogenesis of Diffuse large B cell lymphoma (DLBCL)." (PMID 24312289, 2013). "While HIF-1α is expressed in B-cells during physiological immune activation, HIF-2α overexpression was observed only following malignant transformation, e.g., in Diffuse large B cell lymphoma (DLBCL)." (PMID 31824854, 2019).
endometrial tumors (8 papers, 2007 to 2024). "Mutation of other HIF-1α-modifying enzymes, including prolyl hydroxylase 2, have also been reported in endometrial tumours." (PMID 18096060, 2007). "Our studies provide mechanistic evidence for TM-mediated HIF-1α regulation and suggest its therapeutic potential as a method of blocking angiogenesis in ovarian and endometrial tumors." (PMID 26469226, 2015). "Low AA levels are associated with increased HIF-1α levels and HIF stimulated gene products in human endometrial tumors." (PMID 26547841, 2015). "In conclusion, NFAT5 is expressed in high-grade endometrial tumor tissue and upregulates many genes including HIF1A and PTGS2, which may participate in malignant tumor pathogenesis." (PMID 38612478, 2024). "Compared to non-neoplastic tissue, endometrial neoplasms showed a lower concentration of ascorbate, which, in turn, was associated with HIF-1α activation." (PMID 35215535, 2022). "The highest levels of HIF-1α were observed in high-grade endometrial neoplasms." (PMID 35215535, 2022). "Vitamin C has been proposed to reduce the activity of a key protein called hypoxia inducible factor-1 alpha (HIF-1α), which is involved in endometrial tumour cell survival." (PMID 33946913, 2021).
Lung Squamous Cell Carcinoma (8 papers, 2019 to 2023). "Recently, palbociclib in combination with taxanes, was shown to increase apoptosis and reduce HIF-1α in a pre-clinical model of squamous cell lung cancer." (PMID 36686695, 2022). "According to the data from TCGA database, HIF-1α mRNA was elevated in lung squamous cell carcinoma (LUSC) tissues (n = 486) compared with normal tissues (n = 50)." (PMID 34013042, 2021). "Using The Cancer Genome Atlas Lung Squamous Cell Carcinoma (TCGA-LUSC) database, we divided patients with LUSC into two groups based on low or high HIF1α expression." (PMID 34362882, 2021).
myeloid leukemia (8 papers, 2011 to 2025). A clonal proliferation of myeloid cells and their precursors in the bone marrow, peripheral blood, and spleen. "Studies in different human in vitro models, such as THC-1 myeloid leukaemia, macrophages, and epithelial ovarian cancer cell lines, demonstrated that LPS increases HIF1α transcription." (PMID 40003076, 2025). "With this article we will provide an updated summary of the studies describing the regulation and function of HIF1α and HIF2α in blood malignancies, spanning from acute to chronic, lymphoid to myeloid leukemias." (PMID 36059690, 2022). "In myeloid leukaemia cells SCF triggers accumulation of hypoxia-inducible factor 1 alpha (HIF-1α), an inducible subunit of the HIF-1 transcription complex." (PMID 21799876, 2011). "We report that SCF affects the GSH antioxidative system in THP-1 human myeloid leukaemia cells while inducing HIF-1α accumulation and a moderate increase in thiobarbiturate-reactive species (TBRS)." (PMID 21799876, 2011). "The exact mechanisms leading to SCF-induced HIF-1α accumulation in myeloid leukaemia cells are unknown." (PMID 21799876, 2011). "However, it is unknown how SCF impacts on HIF-1α accumulation in human myeloid leukaemia and mast cells." (PMID 21799876, 2011). "The robustness of the GSH antioxidative system in myeloid leukaemia cells and mast cells is, however, unknown and it is unclear whether this system and redox-dependent mechanisms in general play a role in SCF-induced HIF-1α accumulation." (PMID 21799876, 2011). "Here we show that SCF induces HIF-1α accumulation in THP-1 human myeloid leukaemia cells but not in LAD2 mast cells." (PMID 21799876, 2011). "Firstly, we established whether SCF is able to induce HIF-1α accumulation and, at the same time, affects the GSH-dependent antioxidative system in THP-1 human myeloid leukaemia cells." (PMID 21799876, 2011). "We conclude that SCF leads to a significant accumulation/activation of HIF-1α in human myeloid leukaemia THP-1 cells but not in LAD2 human mast cells." (PMID 21799876, 2011). "Additionally, unlike the inhibition of HIF1α observed in certain cell lines, HIF1α was activated in myeloid leukemia cell lines upon EF-24 treatment." (PMID 40986633, 2025). "However, it has been reported that mitogen-activated protein (MAP) and extracellular signal-regulating kinase (ERK) kinase (MEK) as well as phosphoinositide 3-kinase (PI3 kinase) but not p38 MAP kinase, play a role in SCF-induced HIF-1α accumulation in human myeloid leukaemia cells." (PMID 21799876, 2011).
pancreatitis (8 papers, 2014 to 2026). Inflammation of the pancreas. "Studies have shown that B cells suppress pancreatic regeneration, and their trafficking and/or function are modulated by hypoxia and HIF1α in the setting of pancreatitis." (PMID 39546499, 2024). "The HIF-1α inhibitor 2ME2 attenuated the severity of the pancreatitis and PALI, while the lung edema and alveolar-capillary barrier disruption were significantly ameliorated compared with those in the untreated PALI group." (PMID 25120621, 2014). "The influence of post-translational modifications in this process is illustrated by the action of MLN4924, a neddylation inhibitor, which exacerbates pancreatitis by boosting CCL5 secretion through hypoxia-inducible factor 1 alpha (HIF1α)-mediated gene expression." (PMID 38891952, 2024). "As loss of Prdm3 exaggerated inflammation, we speculate that dysregulation of Hif1a expression might contribute to the dramatic effects of Prdm3 depletion on pancreatitis." (PMID 32179733, 2020). "Given that loss of Prdm3 exaggerated inflammation, we speculate that dysregulation of Hif1a expression might contribute to the dramatic effects of Prdm3 depletion on pancreatitis." (PMID 32179733, 2020).
prostate intraepithelial neoplasia (8 papers, 2006 to 2025). A neoplastic proliferation of the epithelial cells that line the acini and the ducts of the prostate gland. "In PTEN-deficient mouse models of PCa, HIF-1α activation has been detected early during prostatic intraepithelial neoplasia, coinciding with the onset of hyperplasia when cell proliferation begins to exceed oxygen supply." (PMID 41007281, 2025). "For example, prostatic intraepithelial neoplasia is initially hypoxic, and the presence of Hif1a promotes malignant progression." (PMID 38139035, 2023). "HIF1α was also overexpressed in preneoplastic and premalignant lesions such as colonic adenoma and prostate intraepithelial neoplasia." (PMID 24567056, 2014). "Even the hyperproliferation of prostate epithelial cells, in situ, driven by loss of the tumour suppressor, PTen, is sufficient for the activation and accumulation of HIF-1α at the very early prostate intraepithelial neoplasia (PIN) stage, with inflammatory and HIF-1α-driven miRNA expression." (PMID 40806577, 2025). "RAD-001 has been shown to completely reverse the prostate intraepithelial neoplasia (PIN) phenotype in murine transgenic AKT models; in addition mTOR-dependent regulation of HIF-1α may produce an antiangiogenic effect." (PMID 16983403, 2006).
pulmonary edema (8 papers, 2012 to 2025). Accumulation of fluid in the lung tissues causing disturbance of the gas exchange that may lead to respiratory failure. "HIF-1α is higher in hypoxia, which can cause high-altitude pulmonary edema, and HIF-1α may cause inflammation." (PMID 37165489, 2024). "Considering high-altitude pulmonary edema, it was possible to identify a distinct, specific subset of monocyte linked with down-regulation of HIF-1α that might be implicated in the development of the disease." (PMID 37374024, 2023). "Our experimental data corroborate these findings, indicating that increased levels of HIF-1α and VEGF intensify the pathological processes associated with pulmonary edema." (PMID 40766765, 2025). "Collectively, these findings suggest that the reduced mortality observed following HPS patient oxygenation may be at least partly derived from inhibiting VEGF/HIF-1α responses which result in a concomitant reduction in hypoxia-directed pulmonary edema." (PMID 22956954, 2012). "The classical HIF-1α/VEGF signaling pathway also exerts an important role in the pathogeneses of ALI and pulmonary edema." (PMID 36850013, 2023).
rhabdomyosarcoma (8 papers, 2013 to 2025). A rare aggressive malignant mesenchymal neoplasm arising from skeletal muscle. "More recently, pharmacological targeting of the HIF1α signaling pathway has been shown to inhibit rhabdomyosarcoma growth in xenograft models." (PMID 24216979, 2013). "Hypoxia inducible factor-1 α (HIF-1α) has been identified as an important novel target in apoptosis resistance of pediatric tumors such as Rhabdomyosarcoma (RMS) and Ewing’s sarcoma (ES)." (PMID 23590596, 2013). "Several lines of evidence suggest a role HIF1α in rhabdomyosarcoma tumorigenesis." (PMID 24216979, 2013). "Hypoxia has been shown to upregulate IL-8 expression in human rhabdomyosarcoma cell lines, in a manner that is independent of HIF-1α activity." (PMID 24220935, 2014).